LINC01824 (long independently transcribed non-coding RNA 1824)
Gene: Long non-coding RNA gene on chromosome 2 (6,495,651 to 6,511,839, forward strand). Ensembl gene ENSG00000226488.
Diseases named in the same sentence as LINC01824 in open-access papers:
LINC01824 is named in the same sentence as 1 disease in open-access papers, as found by Europe PMC text mining. Sharing a sentence is not in itself a finding about the gene and the disease.
LINC01824 shares sentences with these, for which no sentence is quoted: prostate carcinoma (1 paper).